NDE1 (nudE neurodevelopment protein 1)
Diseases named in the same sentence as NDE1 in open-access papers (continued):
Sharing a sentence is not in itself a finding about the gene and the disease.
Lissencephaly (18 papers, 2011 to 2025). A spectrum of malformations of cortical development caused by insufficient neuronal migration that subsumes the terms agyria, pachygyria and subcortical band heterotopia. "Mutations of LIS-1 and NDE1 in human or their knockout in mice cause lissencephaly, a severe brain developmental disorder characterized by brain atrophy and microcephaly with severe mental disability." (PMID 35011575, 2021). "For example, NDE1 mutations in humans can cause lissencephaly, a cortical developmental disease, and overt microcephaly." (PMID 24785679, 2014). "Mutations of LIS-1 and NDE1 in humans cause the brain disorder of lissencephaly and mental illness." (PMID 35011575, 2021). "Despite deficiencies in cortical neurogenesis, lissencephaly is primarily known as a cortical neuronal migration disease, and the neuronal migration defect of Lis1 heterozygous mutation could be significantly enhanced by Nde1 mutations." (PMID 22028625, 2011). "This study identifies the first lissencephaly-associated NDEL1 variant and sheds light on the distinct roles of NDE1 and NDEL1 in nucleokinesis and MCD pathogenesis." (PMID 38194050, 2024). "Targeted deletion of Nde1 in mice is often embryonically or postnatally lethal and the mice have fewer cortical neurons and a much thinner cortex, reminiscent of lissencephaly." (PMID 24785679, 2014). "The cortical developmental disease lissencephaly (smooth brain) is a result of defects in neurogenesis and neuronal migration, and is associated with the protein LIS1 and its binding partner NDE1." (PMID 22028625, 2011). "Cortical disruptions that derive from mutations in genes such as NDE1, LIS1, PP4c, WDR62, CENPE, TCOF1, AGS3, VANGL2 and HTT, are classified as micro- or macro-cephaly, and/or cortical disorganization and abnormal cortical architecture, lissencephaly and simplified gyral patterns." (PMID 25729350, 2015). "NDE1 and its homolog NDEL1 (Nuclear distribution protein nudE-like 1) physically interact with LIS1 (Lissencephaly 1), the first lissencephaly gene identified, and form a complex involved in neuronal proliferation, differentiation, and migration within the brain." (PMID 23637818, 2013).
epilepsy (9 papers, 2012 to 2024). A brain disorder characterized by episodes of abnormally increased neuronal discharge resulting in transient episodes of sensory or motor neurological dysfunction, or psychic dysfunction. "Previously associated with epilepsy in clinical cohorts, the region harbors NDE1 [MIM: 609449], a gene associated with autosomal recessive lissencephaly [MIM: 614019] and microhydranencephaly [MIM: 605013] and whose mutation has been linked to epilepsy." (PMID 38185688, 2024). "Heterozygous deletion of NDE1 specifically may be a prime cause of epilepsy, both focal and idiopathic generalised, associated with 16p13.11 deletion." (PMID 22523559, 2012). "Within the 16p13.11 region, NDE1 has been proposed as the most likely candidate for epilepsy, as well as other neuropsychiatric symptoms." (PMID 36405918, 2022). "Haploinsufficiency of CYFIP1 at 15q11.2, CHRNA7 at 15q13.3, NDE1 at 16p13.11 and PRRT2 at 16p11.2 has been implicated as risk-conferring mechanism for epilepsy and other neurodevelopmental phenotypes." (PMID 25950944, 2015). "Although Nde1 is involved in epilepsy, and adult hippocampal neurogenesis is up-regulated in rodent epilepsy models and after antidepressant treatment, the roles of Nde1 in these processes are less intensively investigated and therefore remains unclear." (PMID 24785679, 2014). "In epilepsy at least, the deletion does not appear to unmask recessive-acting mutations in NDE1, with haploinsufficiency and genetic modifiers being prime candidate disease mechanisms." (PMID 22523559, 2012). "Finally, it is possible that at least in our two patients, loss of NDE1 is not the key contributor to disease (here, epilepsy) associated with 16p13.11 deletion, suggesting that other candidates and mechanisms need to be sought." (PMID 22523559, 2012). "Surgical temporal lobectomy samples from a MTLE case known not to have a deletion in NDE1 and three non-epilepsy cases were included as disease controls." (PMID 22523559, 2012).
lissencephaly 4 (5 papers, 2013 to 2025). Any lissencephaly in which the cause of the disease is a mutation in the NDE1 gene. "Although NDE1 has been associated to microhydranencephaly and lissencephaly-4 (OMIM #605013 and #614019, respectively), our observation supports its role in neurodevelopmental disorders in the absence of cerebral malformations." (PMID 35368691, 2022). "Loss of NDE1 in mouse models causes profound defects in cerebral corticogenesis and neuronal proliferation and migration, and mutations in NDE1 have been associated with extreme microlissencephaly in humans." (PMID 23637818, 2013). "Lissencephaly-4 is the most common clinical manifestation of NDE1 mutations." (PMID 33390896, 2020). "In all, although the MHAC phenotype appears to be linked to severe loss-of-function of NDE1, the more moderate loss-of-function resulting from truncation of the NUDE-C domain and the addition of novel amino acid residues seems to underlie lissencephaly-4." (PMID 33390896, 2020). "It is worth mentioning that although the g.15691175_15691176GC > CT mutation associated with lissencephaly-4 also occurs in the absence of one NDE1 allele, the degree of truncation is not as severe as g.15667332 C > T and does not have any non-native residues such as g.15696821_15696822delGA." (PMID 33390896, 2020).
autism (3 papers, 2013 to 2018). Persistent deficits in social interaction and communication and interaction as well as a markedly restricted repertoire of activity and interest as well as repetitive patterns of behavior. "Copy number variants at the chromosome 16p13.11 locus, which contains the Nde1 gene, have been implicated in a range of neurodevelopmental disorders, including autism, attention deficit hyperactivity disorder, and SZ41–45." (PMID 29769557, 2018).
brain malformations (3 papers, 2009 to 2022).
glioma (3 papers, 2014 to 2024). A benign or malignant brain and spinal cord tumor that arises from glial cells (astrocytes, oligodendrocytes, ependymal cells). "The correlation between E2F4 and LIN9, MCM8, CEP72, POLA1, DBF4, NDE1 or CDKN2C expression in glioma tissues was analyzed using CGGA." (PMID 37349788, 2023). "Overall, the expression of LIN9, MCM8, CEP72, POLA1, DBF4, NDE1 and CDKN2C increase the prognostic risk for patients with glioma." (PMID 37349788, 2023). "Our analysis revealed a significant positive correlation between E2F4 and MCM8, POLA1, DBF4, NDE1 or CDKN2C expression in primary gliomas." (PMID 37349788, 2023). "Interestingly, NDE1 and NDEL1 have been found in gliomas and their expression is highly associated with the activity of glioma cell migration and proliferation." (PMID 24785679, 2014). "Additionally, although Nde1 regulates radial glial functions during development and its function is pivotal for human glioma formation, the astrocytic distribution of Nde1 and Ndel1 has not been investigated extensively." (PMID 24785679, 2014). "Although NDE1 and NDEL1 have been shown to be expressed in some human gliomas, their expression in normal astrocytes has not been well described." (PMID 24785679, 2014).
Intellectual disability (3 papers, 2013 to 2018). "NDE1 (nudE Nuclear Distribution E homologue 1) is a gene in which different mutations result in a wide range of human brain diseases including microcephaly, intellectual disability, ASD, attention-deficit hyperactivity disorder (ADHD) and SCZ." (PMID 29352035, 2018). "CNVs in NDE1 have also been found by others to associate with a range of phenotypically different neurodevelopmental disorders including intellectual disability, ASD, ADHD and SCZ, which suggest that the locus contains dosage-sensitive gene(s) that may play a critical role in neurodevelopment." (PMID 29352035, 2018).
glioblastoma (2 papers, 2022 to 2023). The most malignant astrocytic tumor (WHO grade IV). "In glioblastoma, SRSF3 promotes the exon 7 inclusion of ETV1 and mutually exclusive of the exon 9 of NDE1 to promote tumorigenesis." (PMID 37558679, 2023).
aortic aneurysm (1 paper, 2019). A ruptured aneurysm located in the wall of the proximal portion of the descending aorta proceeding from the arch of the aorta. "In particular, the MYH11 represents the most important candidate for the predisposition to Thoracic Aortic Aneurysm and Dissection, while the NDE1 gene represents the strongest candidate for the neurodevelopmental phenotypes." (PMID 30836598, 2019).
Autoimmunity (1 paper, 2016). The occurrence of an immune reaction against the organism's own cells or tissues. "Therefore, mutations in nde1-1 and nde1-3 attenuate EDS1 mRNA accumulation under conditions inducing autoimmunity in the parental NLS#A3 line." (PMID 27082651, 2016).
bladder cancer (1 paper, 2024). "The CCK‐8 test, transwell assay, scratch assay and colony formation assay were used to confirm the effects of NDE1 on the proliferation, invasion and metastasis of bladder cancer cells." (PMID 38466053, 2024). "Knockdown of NDE1 inhibited the proliferation, invasion and metastasis of bladder cancer cells, and promoted the apoptosis." (PMID 38466053, 2024). "In addition, the results of in vitro experiments demonstrated that the knockdown of NDE1 not only resulted in reduced proliferation, invasion and migration of bladder cancer cells, but also promoted apoptosis." (PMID 38466053, 2024). "The proliferation, invasion and metastasis of bladder cancer cells may be prevented by NDE1 knockdown." (PMID 38466053, 2024). "Furthermore, knockdown of NDE1 promoted the apoptosis of bladder cancer cells." (PMID 38466053, 2024). "In order to fill the research gap pertaining to the impact of NDE1 on the genesis and progression of cancer, our study also included experimental investigations aimed at elucidating the role of NDE1 in facilitating the proliferation, migration and invasion of bladder cancer cells." (PMID 38466053, 2024).
congenital microcephaly (1 paper, 2020). "Pathogenic variants of NDE1 have been linked to congenital microcephaly in humans." (PMID 33390896, 2020).
epilepsy syndrome (1 paper, 2024). A syndrome that has a characteristic cluster of clinical features and/or lectroencephalographic (EEG) findings that reflect underlying epileptic activity. "Ciliary-related NDE1 was consistently included in the 16p13.11 deletions in 23 previously evaluated patients with epilepsy syndromes and eight patients with TAAD." (PMID 39315310, 2024).
heart failure (1 paper, 2023). Inability of the heart to pump blood at an adequate rate to meet tissue metabolic requirements. "NDE1 and MYH11 were involved in the Rho GTPase effectors pathway whose important role in the pathogenesis of vasospasm, hypertension, pulmonary hypertension, and heart failure had been demonstrated." (PMID 36869404, 2023).
Hypertension (1 paper, 2023). The presence of chronic increased pressure in the systemic arterial system. "NDE1 gene was involved in the signaling pathway by Rho GTPases, which could play a critical role in the pathogenesis of hypertension." (PMID 36869404, 2023).
lissencephaly type 1 (1 paper, 2018). "CENP-F has been implicated in dynein recruitment and regulation through a pathway involving Nde1, Ndel1, and Lis1, the product of the lissencephaly type 1 gene (77, –, 79, 90, 91)." (PMID 29748388, 2018).
mental disorder (1 paper, 2014). A disease that has its basis in the disruption of mental process. "While genetic linkage analyses have shown an association of nuclear distribution factor E (NDE1, or NudE) and its ohnolog NDE-like 1 (NDEL1, or Nudel) with mental disorders, the cellular mechanisms remain unclear." (PMID 24785679, 2014). "We have provided the most comprehensive documentation of the expression patterns of Nde1 and Ndel1 in cultured cells as well as in mouse and human brains, and also highlight that dosage effects of these two proteins might contribute to some cases of mental disorder." (PMID 24785679, 2014).
psychiatric disorder (11 papers, 2009 to 2023). A disorder characterized by behavioral and/or psychological abnormalities, often accompanied by physical symptoms. "Several independent studies have implicated chromosome 16p13.11 microduplication and the NDE1 gene as underlying contributors to mental illness and abnormal corticogenesis in humans and rodent models, respectively." (PMID 30401811, 2019). "Studies show that NDE1 is aberrantly expressed in neurological and psychiatric disorders, and binds to DISC1 to mediate the latter’s role in neurogenesis and neural development." (PMID 34981809, 2022). "The extent to which NDE1 actively contributes to psychiatric disorders is still, for the most part, an unresolved question that will require in vivo studies to obtain a definitive answer." (PMID 33390896, 2020). "Thus, variation at the NDE1 locus may alter risk of mental illness, in part through modification of miR-484, and such modification alters treatment response to specific psychoactive medications, leading to the potential for use of this locus in targeting treatment." (PMID 29142105, 2017). "Here we have demonstrated that variations within the NDE1 locus, encoding a protein of the DISC1 network of protein interaction partners, can affect both gene expression levels and medication usage of psychoactive drugs used to treat major mental illnesses." (PMID 29142105, 2017). "This study has, therefore, provided new biological insight into psychiatric disorders for which novel medications could be designed, as well as suggesting that knowledge of an individual's genotype within the NDE1/miR-484 locus may have potential value in the targeting of current therapies." (PMID 29142105, 2017).
cancer (7 papers, 2010 to 2024). A tumor composed of atypical neoplastic, often pleomorphic cells that invade other tissues. "High expression of NDE1 is present in a variety of tumours, which is linked to a bad prognosis for cancer." (PMID 38466053, 2024). "In conclusion, NDE1 has the potential to be a target for immunotherapy since it is associated with the percentage of cancer cells in tumours and other genomic abnormalities, such as spontaneous loss of nucleotides in repetitive DNA strands." (PMID 38466053, 2024). "In summary, our investigation has shown that the expression of NDE1 is significantly elevated in several malignant tumours and is associated with a worse prognosis in numerous cancer types." (PMID 38466053, 2024). "Using the R package ‘pROC’ (v1.17.0.1), ROC curves of NDE1 in various malignancies may be produced to evaluate the diagnostic usefulness of NDE1 in pan‐cancer." (PMID 38466053, 2024). "NDE1 is an excellent diagnostic tool for many different types of cancer." (PMID 38466053, 2024). "We believed that NDE1 was most likely involved in the formation of cancer since it controls cell division by interacting with dynein and can bind to certain proteins implicated in cancer development." (PMID 38466053, 2024). "Multiple studies have shown that a considerable number of tumours have modified NDE1 expression, and many types of cancer also display changed or increased levels of NDE1 methylation." (PMID 38466053, 2024). "Both PAFAH1B1 and DCTN1 are shown to promote cancer in specific cancers, while NDE1 has mutual binding properties with PAFAH1B1 and DCTN1, respectively." (PMID 38466053, 2024). "We used the TIMER2 database and the QUANTISEQ method, respectively, to conduct a correlation study between immune cell infiltration and NDE1 expression in pan‐cancer to examine the connection between the two." (PMID 38466053, 2024). "We obtained the GSEA database and ran KEGG and GO enrichment analyses of NDE1 to learn more about the role that NDE1 plays in the immune regulation of cancer." (PMID 38466053, 2024). "NDE1 was, however, shown to be significantly expressed in the majority of malignancies after examination of matched samples (cancer and paracancerous tissues) from the TCGA and GEO databases." (PMID 38466053, 2024). "Given that NDE1 significantly positively correlates with almost all of the known immune checkpoint genes, it is clear that NDE1 is connected to immunity against cancer tumours." (PMID 38466053, 2024). "In six malignancies, including CHOL (AUC = 0.997), COAD (AUC = 0.931), COADREAD (AUC = 0.923), HNSC (AUC = 0.939), LUSC (AUC = 0.974) and OSCC (AUC = 0.935), the AUC of NDE1 was larger than 0.7 in 16 different forms of cancer." (PMID 38466053, 2024). "Using the TISIDB portal, the link between NDE1 expression level and cancer immune subtypes and molecular subtypes was examined." (PMID 38466053, 2024). "YBX1 was a versatile RNA‐binding protein that was highly overexpressed in multiple cancer types, and NDE1 and ERO1L were the two most DEGs." (PMID 35635121, 2023). "For example, NDE1 was related to the clinical features (Subtype, Tumor/Normal, Stage and Survival) of 8 types of cancer." (PMID 35487956, 2022). "In conclusion, our studies reveal that NDE1 may be an oncogene with potential as a prognostic indicator for cancer." (PMID 38466053, 2024). "This also seems to be a piece of evidence that NDE1 behaves as an oncogene in pan‐cancer." (PMID 38466053, 2024). "The expression level, prognostic impact, gene change, DNA methylation, protein interaction, mRNA m6A modification, ceRNA network, associated gene and function enrichment, and immune‐related effects of NDE1 in pan‐cancer were examined using a range of online analytic tools and the R software package." (PMID 38466053, 2024). "We thus used data mining and tests to investigate the function of NDE1 in pan‐cancers." (PMID 38466053, 2024).
cancer (continued). "We investigated NDE1's expression level, prognostic impact, gene alteration, DNA methylation, protein interaction, m6A mRNA modification, ceRNA network, related gene and function enrichment, and immune‐related effects in pan‐cancer." (PMID 38466053, 2024). "Therefore, it is hypothesised that NDE1 may control the growth of cancer by influencing the processes of cell division and proliferation." (PMID 38466053, 2024). "However, studies examining the connection between NDE1 and cancer is still very rare." (PMID 38466053, 2024). "Together, NDE1 may have a role in the control of the immune system in cancer." (PMID 38466053, 2024). "NDE1 could affect how well immunotherapy works to treat different types of cancer." (PMID 38466053, 2024). "Studies examining the connection between NDE1 and cancer are still very rare or even nonexistent." (PMID 38466053, 2024). "NDE1 expression level showed a substantial positive link with MSI in seven tumours and a significant negative correlation with MSI in four cancers." (PMID 38466053, 2024).
neurodevelopmental disorder (7 papers, 2018 to 2025). A behavioral and cognitive disorder with onset during the developmental period that involves impaired or aberrant development of intellectual, motor, or social functions. "In this region, NDE1 and miR-484 are the two of the genes that are considered major contributors to the risk of neurodevelopmental disorders." (PMID 36292681, 2022). "Taken together, the genetic and biological evidence for DISC1 and NDE1 suggest a shared ‘risk’ pathway in neurodevelopmental disorders although the precise mechanism(s) of action has remained elusive." (PMID 30401811, 2019). "This study demonstrates a potential role for genes within the chromosome 16p13.11 microduplication (and NDE1 in particular) in human corticogenesis and implicates dysregulation of NFκB as an important mechanistic pathway in neurodevelopmental disorders." (PMID 30401811, 2019).